SMIM35 (small integral membrane protein 35)
Synonyms: TMPRSS4-AS1
Gene: Protein-coding gene on chromosome 11 (118,003,634 to 118,088,299, reverse strand). Ensembl gene ENSG00000255274.
Subcellular location: Membrane
Gene Ontology:
Cellular component: membrane
Homologues: Orthologues: chimpanzee SMIM35 (100% identical), macaque SMIM35 (98% identical), guinea pig SMIM35 (93% identical), rabbit SMIM35 (91% identical), mouse Smim35 (88% identical), pig SMIM35 (88% identical), rat Smim35 (88% identical).